EGFR (epidermal growth factor receptor)
Diseases named in the same sentence as EGFR in open-access papers (continued):
Sharing a sentence is not in itself a finding about the gene and the disease.
tumor (continued). "Those few studies have revealed that Id-1 is involved in tumour progression and associated with poor prognostic factors, but the relationship between Id-1 and EGFR and VEGF has not been studied." (PMID 19014499, 2008). "It is known that EGFR is involved in carcinogenesis in many tumours." (PMID 19014499, 2008). "EGFR targeted radiotherapy might also be possible if a tumor and its metastases have a strong EGFR expression to ensure higher tumor uptake than in most normal tissues or local delivery of the targeting agent can be made." (PMID 18700025, 2008). "Localization of EGFR within tumour cells was eithermembranous, cytoplasmic, or both." (PMID 18769552, 2008). "Among the 25 primary tumours, three ‘hotspot’ and two non-classical EGFR mutations were found; none of the corresponding metastases had the same mutation pattern." (PMID 19238633, 2008). "On the basis of these findings, at the present time, we consider that only the genetic differences unequivocally distinguish EGFR-dependent tumours, which are likely to be sensitive to TKIs from the tumours that could be resistant to these agents." (PMID 19238633, 2008). "These authors made the logical hypothesis that gefitinib leading to G1 growth arrest of EGFR-dependent tumour cells may, following continuous administration, attenuate the effects of tubulin inhibitors – such as paclitaxel – which act primarily during mitosis." (PMID 18506149, 2008). "In addition, the dominant mechanism for tumour suppression is the concomitant decrease in tumour protein expressions of mTOR and the EGFR." (PMID 18797454, 2008). "Association between Id-1, EGFR, VEGF, tumour grade and Dukes' stage." (PMID 19014499, 2008). "In fact, EGFR has been shown to play a role in tumour development and progression." (PMID 19014499, 2008). "Interestingly, patients harbouring these tumours displayed a 5-year overall survival rate that was similar to that of patients with tumours that overexpress both EGFR and cortactin (22 vs 19%, respectively)." (PMID 18268492, 2008). "We conclude that there is substantial discordance in EGFR and K-RAS mutational status between the primary tumours and corresponding metastases in patients with NSCLC and this might have therapeutic implications when treatment with TKIs is considered." (PMID 19238633, 2008). "In addition, several studies showed a relationship between high EGFR levels and high grade tumours and poor prognosis." (PMID 19014499, 2008). "Our findings demonstrate that circulating tumor cells express receptors and activated signaling kinases of the EGFR/HER2/PI3K/Akt pathway, which could be used as targets for their effective elimination." (PMID 18822183, 2008). "Between March 2005 and January 2006, 118 patients were prospectively screened from 15 institutions; 117 of them underwent EGFR mutation analysis (tumour tissue was not available for one patient)." (PMID 18283321, 2008). "Moreover, continued activation of PI3K/Akt signalling, which triggers mTOR, seems to contribute to the development and maintenance of an EGFR-resistant phenotype, and it has been found in tumour samples from cancers patients failed in EGFR-targeted therapy." (PMID 18319715, 2008). "Although it remains unclear whether this cell line expresses the EGFR, maximal tumor activity uptake was obtained between 30 and 60 min post injection of the tracer, followed by a decrease to background tissue levels after 5 h." (PMID 18991714, 2008). "Interestingly, these authors showed that EGFR-positive tumours had a higher expression of Ki-67 and survivin transcripts." (PMID 18769552, 2008). "Loss of tumor suppressor gene RB, inactivation of CDK-inhibitor, and overexpression of epidermal growth-factor receptor might contribute to the development of neoplasm." (PMID 18721462, 2008).
tumor (continued). "There are recent preclinical background and early clinical trials that indicate that targeting both EGFR pathway and tumour angiogenesis may be a useful strategy in the management of several tumour pathologies." (PMID 18577994, 2008). "The EGFR-testing had shown a strong overexpression in all tumor cells." (PMID 17927839, 2007). "Thus, it was suggested that in EGFR-expressing tumor cells with concomitant amplification(s) of PI3K/Akt signaling, combined blockade of the EGFR tyrosine kinase and Akt should be considered as a therapeutic approach." (PMID 19384426, 2007). "Furthermore, it has been reported that EGFR-HER-2 heterodimers are rate-limiting in the EGF-mediated proliferation of tumour cells." (PMID 17622245, 2007). "In our exploratory subset analysis, tumour response was observed in 16 out of 19 patients with both EGFR mutations and no smoking history." (PMID 17325698, 2007). "Our data indicates that downregulation of HIF-1α is associated with positive therapeutic responses of cancer cells to EGFR-targeted therapy and suggest further investigation using HIF-1α as an indicator of tumor response to EGFR-targeted therapy in preclinical studies and in the clinical setting." (PMID 17931419, 2007). "It is difficult to obtain sufficient tumour DNA from non-surgical tissue samples, for example, those derived from bronchoscopy that allow detection of EGFR mutations by direct sequencing." (PMID 17848912, 2007). "Importantly, both EGFR- and HER-2-positive tumours were observed in 18% of all patients, out of which 75% showed EGFR and HER-2 expression in individually distinct regions." (PMID 17622245, 2007). "The prominent role of EGFR signalling in many tumour types has prompted the development of pharmacological inhibitors such as the anilinoquinazolines (gefitinib and erlotinib), which disrupt EGFR kinase activity by binding the ATP pocket within the catalytic kinase domain." (PMID 17533397, 2007). "Moreover, these mice develop spontaneous tumors in different organs supporting a role for Mig6 as a novel tumor suppressor of EGFR-dependent malignancies." (PMID 19662191, 2007). "Both EGFR and HER-2 expressions in the same patients were observed in 12 cases (18%), in which expressions of both EGFR and HER-2 were seen in the same tumour regions in two cases, and EGFR and HER-2 expressions were seen in individually distinct regions in nine cases." (PMID 17622245, 2007). "The effectiveness of gefitinib therapy in our patient could be explained in part by the presence of an activating mutation of epidermal growth factor receptor (EGFR) gene, L858R in exon 21, which was identified in the primary tumor." (PMID 18021415, 2007). "The family of signal transduction proteins that has received the most attention to date are the Epidermal Growth Factor Receptor (EGFR) family, most likely as several of its members are manifestly involved in stimulating tumour growth and concepts of drug action are clear." (PMID 17211472, 2007). "Indeed, patients whose tumours harbour ‘other’ variants of EGFR mutations had a higher, but not statistically significant, DCR when compared with patients bearing wild-type EGFR." (PMID 18000506, 2007). "However, patients with EGFR overexpressing tumours (⩾85% tumour cell staining) demonstrated a significantly worse prognosis (35.0 months (23.0–58.0)) than those with no overexpression (87.0 months (69.0–103.0))." (PMID 17311026, 2007). "This 'micro-macro' framework was then extended 'top-down' by incorporating an EGFR molecular interaction network so that molecular dynamics at the protein level could be related to multi-cellular tumor growth patterns." (PMID 18154660, 2007).
tumor (continued). "According to the data for 1170 patients, more than 70% of NSCLCs with EGFR mutations respond to EGFR-TKIs, whereas 10% of tumours without EGFR mutations do so." (PMID 17325698, 2007). "The average EGFR cutoff scores were obtained and included 18% for predicting complete response, 15% for predicting complete or partial response, 85% for T stage, and 10-year survival, 75% for N stage, 82% for tumour grade and 80% for vascular invasion." (PMID 17311026, 2007). "Expression of either EGFR mutant leads to the development of adenocarcinoma similar to human bronchioloalveolar cell carcinoma and withdrawal of doxycycline to reduce expression of transgene or erlotinib treatment resulted in tumour regression." (PMID 17325698, 2007). "In two patients the tumour samples was positive for an EGFR mutation and the serum sample was negative." (PMID 17848912, 2007). "The epidermal growth factor-receptor (EGFR) is a particularly interesting target as it plays an important role in regulation of cellular proliferation, differentiation and survival of epithelial cells and tumours of epithelial cell origin." (PMID 17224925, 2007). "Furthermore, while L858R-treated tumor cells demonstrated a dramatic decrease in phospho-EGFR staining, the treated C/L858R+T790M tumor cells continued to display reactivity with phospho-EGFR antibody." (PMID 17726540, 2007). "Patients with EGFR mutations in both tumour samples and serum samples had a significantly longer median PFS than the patients without EGFR mutations (194 vs 55 days, P=0.016, in tumour samples; 174 vs 58 days, P=0.044, in serum samples)." (PMID 17848912, 2007). "Additionally, aberrant EGFR signalling imparts SCCHN cells with classic tumour cell characteristics, including decreased apoptosis, enhanced invasiveness, migration, angiogenesis and metastasis." (PMID 17224925, 2007). "There were no EGFR mutations detected in either the tumour sample or serum sample from 33 of the patients." (PMID 17848912, 2007). "RWGT2 cells in vitro or in tumours exhibited relatively high levels of EGFR phosphorylation." (PMID 17533397, 2007). "However, it should be noted that their definition of increased gene copy number included both gene amplification and high polysomy (more than 40% of tumour cells have more than four copies of the EGFR gene)." (PMID 17325698, 2007). "Furthermore, we demonstrate that tumour cell growth can be attenuated by blocking EGFR, alone or in combination with YB-1 inhibition, providing new possibilities for the treatment of this highly aggressive disease." (PMID 17875215, 2007). "Median progression-free survival time was significantly longer in the patients with EGFR mutations than in the patients without EGFR mutations (194 vs 55 days, P=0.016, in tumour samples; 174 vs 58 days, P=0.044, in serum samples)." (PMID 17848912, 2007). "It has been reported that EGFR targeting in tumours may also modulate the migration and formation of tube-like structures of vascular endothelial cells." (PMID 17592499, 2007). "However, not all tumors with these mutations respond to TKIs, and other genetic changes—for example, amplification (multiple copies) of the EGFR gene—also affect tumor responses to TKIs." (PMID 17455987, 2007). "Such tumours express YB-1 and EGFR in 73% and 57.1% of the BLBC cases, respectively." (PMID 17875215, 2007). "In one patient, the serum sample was positive for an EGFR mutation and the tumour sample was negative." (PMID 17848912, 2007). "Apparent inverse relationship between smoking and EGFR mutations was thus due to dilutional effect of EGFR-mutated tumours by EGFR nonmutated tumours." (PMID 17325698, 2007). "Compounds such as cetuximab, gefitinib, and erlotinib could prove valid for targeting tumours expressing EGFR in patients selected according to this marker and may represent a novel therapeutic strategy in patients with CUP." (PMID 17876336, 2007).
tumor (continued). "This positive autoregulatory feedback loop that restores EGFR protein levels to enable tumour growth in hypoxic conditions may also occur in other conditions." (PMID 17311025, 2007). "The literature review on the role of EGFR-TK signalling in tumour response to radiation therapy indicates that EGFR-TK activity in tumours can block the cytotoxic effects of radiation therapy and enhance tumour repopulation, resulting in the failure of local tumour control." (PMID 21614219, 2006). "Skin has been used as a surrogate for tumour in measuring the molecular effects of EGFR-targeted agents on EGFR, the ability of EGFR to transmit signals to kinases downstream in the signalling cascade and the responses mediated through EGFR, cell cycle progression and proliferation." (PMID 16622465, 2006). "EGFR gene amplification may be homogenously distributed over the tumor areas in a tissue section or may be confined to certain cells." (PMID 16911776, 2006). "Expression of EGFR has been shown to be crucial for cancerogenesis in different tumor entities." (PMID 16846514, 2006). "As these drugs are target-specific, their combination with other targeted agents or with chemotherapy could, in theory, improve outcome when EGFR overexpression is present in a basal-like tumour." (PMID 17088909, 2006). "Tumor samples obtained from H. Lee Moffitt Cancer Center and Research Institute (Tampa, Fl) were used for hybridization to Affymetrix U133A arrays and assayed by immunohistochemical (IHC) methods, scoring for phosphorylated EGFR (pEGFR) as previously reported." (PMID 17096850, 2006). "Albeit very little is known about physiological function and cancer relevance of the nuclear EGFR pathway until recent years, EGFR has been consistently detected in the nuclei of cancer cells and primary tumour specimens of various origins as well as in those of other highly proliferative tissues." (PMID 16434982, 2006). "Combining both of the tumor data sets, our predictor of EGFR TKI sensitivity suggests that 80% of the tumors may be sensitive." (PMID 17096850, 2006). "The EGFR gene is a protooncogene and plays a key role in the development of human tumours." (PMID 21614219, 2006). "Furthermore, classification of the tumors using 50- and 180-genes models identify a majority of the pEGFR positive samples in both datasets, as well as capturing 5 of 6 EGFR mutants in the Duke tumor dataset." (PMID 17096850, 2006). "This suggests that the administration of single agent EGFR TK inhibitors can result in significant clinical benefit and more work needs to be carried out on patient selection for targeted therapy trials based perhaps on a tumour genotype or tumour phenotype." (PMID 16570047, 2006). "Clinical studies reveal that it is the mutations within the EGFR-TK domain that predict the response to the EGFR inhibitor; not the level of tumour EGFR expression." (PMID 21614219, 2006). "Confirmation of the optimal cut-off values in the frequency of tumor cells displaying high gene copy number for identification of EGFR FISH positive patients based on the best fit analysis of clinical outcome to the molecular target therapies is also under way." (PMID 16911776, 2006). "Only two of 14 patients with the wild-type EGFR gene showed gefitinib-induced tumour regression." (PMID 17047654, 2006). "Some investigators have tried to improve the sensitivity of detection of EGFR mutations in samples containing a mixture of tumour and normal cells." (PMID 17060940, 2006). "Among the 11 patients with EGFR mutations, 10 showed tumour regression after gefitinib treatment and one showed no cancer progression over 1 year." (PMID 17047654, 2006). "These patients were initially stratified into six FISH groups according to an increasing number of copies of the EGFR gene in their tumor cells (disomy, low trisomy, high trisomy, low polysomy, high polysomy, and gene amplification) and these groups were evaluated for clinical outcome." (PMID 16911776, 2006).
tumor (continued). "The detailed type of EGFR mutation did not correlate with gender, smoking status, p-stage, histological subtype, grade of tumour differentiation (data not shown)." (PMID 16052218, 2005). "Up till now, the effects of EGFR on chemo-sensitivity were less clear and were suggested that it might be depending on particular tumor cell lines or cell types or particular drugs used for the experiment." (PMID 15987532, 2005). "Despite similar amounts of EGFR mRNA, cell lines (vs tumours) overexpressed EGFR protein." (PMID 15956968, 2005). "In conclusion, mutations in the EGFR gene were found in approximately half of our Japanese adenocarcinoma patients, and were more common in tumours developed in nonsmokers." (PMID 16052218, 2005). "Epidermal growth factor receptor mutations were, however, more frequently observed in tumours with BAC component than those without BAC component (78.9 vs 42.9%, P<0.001, odds ratio: 5.0, 95% confidence intervals: 2.0–12.6)." (PMID 16052218, 2005). "In addition, inhibition of EGFR signalling has been shown to induce selective apoptosis in tumour endothelial cells in an orthotopic model of human renal cell carcinoma metastasis in bone." (PMID 15928657, 2005). "High expression of epidermal growth factor receptor (EGFR) has been observed in a variety of tumours, including the lung and liver, which has been shown to correlate with disease progression, poor survival, poor response to therapy and the development of resistance to cytotoxic agents." (PMID 15841081, 2005). "EGFR positivity was observed in 29 of 45 tumors (64%) and was associated with neither clinical tumor stage nor clinical nodal stage." (PMID 15967033, 2005). "Patients with tumours harbouring EGFR amplification had a trend toward shorter DFS and OS." (PMID 16280056, 2005). "Collectively, these data suggest that ZD6474 may be an effective treatment against tumours with acquired or intrinsic EGFR resistance, because of its ability to inhibit VEGF signalling." (PMID 15928657, 2005). "High level of EGFR expression also correlates with increased tumour resistance to radiation, suggesting that EGFR may mediate radioresistance of cancer cells." (PMID 15655552, 2005). "In accordance with this, overexpression of EGFR in germline tumour cells showed an increase in drug resistance, suggesting that a lack of EGFR, at least in part, contributes to the drug sensitivity of germline tumours." (PMID 15655552, 2005). "By contraries, EGFR mutations were less frequently observed in tumours with solid component than those without solid component (34.2 vs 67.1%, P=0.001, odds ratio: 0.25, 95% confidence intervals: 0.11–0.61)." (PMID 16052218, 2005). "Those tumours with activating mutations in the EGFR gene but which lack PTEN may be resistant to gefitinib, as PTEN is located downstream of the EGFR." (PMID 15870831, 2005). "It remains to be determined whether therapeutic interventions will exploit this using higher affinity analogues or indirect augmentation of the described pathway that crossattenuates the autocrine EGFR signalling pathway in tumour promotion." (PMID 15655536, 2005). "No tumours with EGFR mutations had any K-ras codon 12 mutations, which were well-known smoking-related gene mutations." (PMID 16052218, 2005). "Patients deemed "unresectable" due to extensive tumor invasion and multifocality of disease may have been more likely to have the over expression of the EGFR or the EGFRvIII." (PMID 16236164, 2005). "Furthermore, we have demonstrated that the tumour stroma was rich in EGFR gene alterations compared to the epithelium." (PMID 15841079, 2005). "Overall, these results suggest that ZD6474 can inhibit EGFR-dependent tumour growth, and also that the magnitude of inhibition may depend upon the expression of mutant EGFR." (PMID 15928657, 2005). "Furthermore, dsRNA specific for EGFR inhibited tumor growth in vivo both in size by 75.06 % and in weight by 73.08 %." (PMID 15987532, 2005).